CTLA4 (cytotoxic T-lymphocyte associated protein 4)
Diseases named in the same sentence as CTLA4 in open-access papers (continued):
Sharing a sentence is not in itself a finding about the gene and the disease.
melanoma (continued). "There is a new era with the introduction of immunotherapy: CTLA‐4 antibody targeting agents and PD‐1 and PDL‐1 inhibitors have been shown to be effective in the treatment of metastasized melanoma, including in patients with brain metastases from melanoma (MDM)." (PMID 40485242, 2025). "Furthermore, the administration of recombinant murine IL-17 A in combination with dual checkpoint blockade targeting CTLA-4 and PD-1 significantly enhances CD8+ T cell infiltration and effectively suppresses melanoma progression." (PMID 40866941, 2025). "Combinatorial ICI therapy using anti-CTLA4 and anti-PD1 controlled melanoma growth in vivo." (PMID 40313772, 2025). "Other PRMTs also play immunomodulatory roles: in melanoma, the PRMT4 inhibitor EZF2302 restores sensitivity to anti-CTLA-4 therapy, while the PRMT7 inhibitor SGC3027 enhances anti-tumor T cell responses and reduces tumor burden when combined with ICB by promoting immune cell infiltration." (PMID 41204384, 2025). "Although melanoma remains one of the deadliest cancers, accounting for approximately 59,000 deaths worldwide, IO improved 5-year OS rates in stage IV melanoma from 15% to 52% with combination anti-PDL-1 and anti-CTLA-4 therapy." (PMID 40647451, 2025). "In a study of melanoma, it was reported that the combination of local radiation therapy and anti-CTLA-4 immunotherapy enhanced the therapeutic outcome in comparison to anti-CTLA-4 monotherapy by enhancing the infiltration of CD8+ T cells." (PMID 40342408, 2025). "Regarding the first approach we took advantage of the only two identified in the literature studies containing single cell data from melanoma patients following immunotherapy, particularly PD1, CTLA4 or combined inhibition and concurrently demonstrating the response status of these patients." (PMID 41372921, 2025). "Along similar lines, RIG-1 signalling was shown to be critical for systemic tumour control following anti-CTLA-4 therapy in preclinical models, and higher expression of RIG-1 correlated with prolonged survival and durable responses to anti-CTLA-4 in melanoma patients." (PMID 41188872, 2025). "Dual checkpoint blockade, such as the combination of ipilimumab (CTLA-4 inhibitor) and nivolumab (PD-1 inhibitor), has demonstrated superior efficacy and received FDA approval for multiple cancers, including melanoma, NSCLC, RCC, HCC, and microsatellite instability-high (MSI-high) colorectal cancer." (PMID 40950404, 2025). "Later Phase II investigations in melanoma proceeded fast, resulting in a landmark Phase III study that served as the foundation for the FDA’s approval of ipilimumab, a humanized anti-CTLA-4 monoclonal antibody, for the treatment of metastatic melanoma." (PMID 40606990, 2025). "Thus, we screened a cohort of 48 melanoma patients that were longitudinally sampled throughout therapy, in this case a regimen of anti–CTLA-4, anti–PD-1, or combined CTLA-4 and PD-1 blockade." (PMID 39808498, 2025). "Moreover, we examined the correlation between CTHRC1 expression and immunotherapy markers, including CD274, PDCD1, CTLA4, and LAG3 in colon cancer, thyroid cancer, and melanoma." (PMID 39052013, 2024). "CD274, PDCD1, CTLA4, and LAG3 were significantly positively correlated with CTHRC1 expression in colon cancer and thyroid cancer; while only CTLA4 was significantly positively correlated with CTHRC1 expression in melanoma." (PMID 39052013, 2024). "The non-redundant expression of PD-1 and CTLA-4 makes them promising targets for combination therapy, showing efficacy in advanced-stage melanoma, RCC, and NSCLC." (PMID 38785789, 2024). "In addition, in melanoma, the Tsurv model performed well in the anti-PD1 regimen, anti-CTLA-4 regimen and combination therapy cohorts." (PMID 38343549, 2024). "For example, patients with advanced melanoma that is nonresponsive to anti-CTLA-4 or anti-PD-1/PD-L1 therapy have higher frequencies of genetic alterations associated with IFN-γ signaling defects compared to responsive patients." (PMID 38829686, 2024).
melanoma (continued). "The discovery that blocking CTLA-4 can enhance antitumor immunity has led to the development of CTLA-4 inhibitors, such as ipilimumab, the first immune checkpoint inhibitor authorized by the United States Food and Drug Administration (FDA) for melanoma treatment." (PMID 39483536, 2024). "Additionally, Gc-/- mice bearing 5555 BrafV600E melanoma or MCA-205 fibrosarcoma tumors displayed greater responses to anti-PD1 and anti-CTLA-4 checkpoint blockade immunotherapies than C57BL6/J wild type (WT) mice." (PMID 38662827, 2024). "The Lenvamel study aimed to investigate the efficacy and safety of lenvatinib combined with anti-PD-1 in a French multicenter real-world patient cohort with advanced melanoma refractory to prior treatment with anti-PD-1 with or without anti-CTLA-4." (PMID 38956747, 2024). "In total, 17 (non-mucosal) melanoma metastases from anti-CTLA4 resistant (CTLA4res) and 21 from anti-PD1 resistant (PD1res) cases were analyzed." (PMID 38594286, 2024). "Melanomas can manipulate immune checkpoints through PD1, PD-L1/2, and CTLA-4." (PMID 38586368, 2024). "In another study, myocarditis could be induced in male and female C57BL/6J mice that were either healthy or burdened with colorectal cancer (MC38), melanoma (B16F10), and breast cancer (EO7710) upon anti-PD-1 and anti-CTLA-4 combination therapy." (PMID 39247203, 2024). "In BRAF V600-mutated melanomas, high levels of IL-17 gene expression supported the anti-tumor effects of dual ICI with anti-PD-L1 and anti-CTLA-4, but not with single anti-CTLA-4 or anti-PD-1 therapy." (PMID 39906741, 2024). "With the recent approval of anti-LAG-3 ICIs for the treatment of metastatic melanoma, a better understanding of the role of the melanoma TME and mechanisms mediating patient response to anti-PD-1 monotherapy compared to combination therapy with anti-CTLA-4 or LAG-3, is clearly needed." (PMID 38217840, 2024). "Surprisingly, the studies demonstrated the predictive role of tumor cell HLA class I expression in melanoma patients treated with the CTLA-4 inhibitor ipilimumab but not in those receiving PD-1 blocking agents." (PMID 39766316, 2024). "Similarly, radiotherapy combined with antibodies against CTLA4 and PDL1 increased abscopal response rates in a study on melanoma." (PMID 39228005, 2024). "Ipilimumab (Yervoy, Bristol-Myers Squibb Company), which functions by inhibiting the co-inhibitory receptor CTLA-4, was the first immune checkpoint inhibitor (ICI) found to extend survival in metastatic melanoma, leading to its FDA approval for the treatment of melanoma in 2011." (PMID 39123418, 2024). "On the other hand, expression of MHC-II, which correlates with IFN-γ, has been shown to predict melanoma response to anti-PD-1 but not to anti-CTLA-4 therapy." (PMID 37877810, 2024). "For patients with advanced melanoma treated with a combination of anti-PD-1 and anti-CTLA-4 monoclonal antibodies (mAb), the five-year survival rate now exceeds 50%." (PMID 38928238, 2024). "In summary, the frequencies of genetic alterations in melanoma driver genes were not different in anti-CTLA4 and anti-PD1 resistant and ICB naïve metastatic melanomas." (PMID 38594286, 2024). "Although immune checkpoint inhibitors, such as anti-CTLA-4 and PD-1, have demonstrated promising anti-tumor effects in the clinical treatment of melanoma, a subset of patients does not respond to these immunotherapeutic agents." (PMID 39493767, 2024). "In fact, in a mouse melanoma model, treatment with a small molecule inhibitor of CAIX increased frequency of effector TH1 skewed CD4+ T cells and increased the response of these tumors to immune checkpoint therapy with anti-PD-1 and anti-CTLA-4 antibodies." (PMID 38510243, 2024).
melanoma (continued). "In particular, the phase II LEAP-004 study, evaluating combined lenvatinib and pembrolizumab in 103 patients with advanced melanoma progressing on ICI, showed an ORR of 21.4%, reaching up to 33.3% in patients previously treated with anti-PD-1 and anti-CTLA-4 combination therapy." (PMID 38956747, 2024). "In the immune microenvironment of CRC, unlike in melanoma, ICOS expression is associated with high expression of CTLA‐4 and PD‐1 on lymphocytes." (PMID 38506253, 2024). "Interestingly, in a murine model of implanted melanoma, neutrophils mediated tumor eradication by melanoma-specific CD4+ T cell therapy in combination with OX40 co-stimulation or CTLA-4 blockade." (PMID 39126091, 2024). "Immune-activating anti-CTLA4 and anti-PD1 monoclonal antibodies (alone or in combination) are being used to treat advanced melanoma patients and can lead to durable remissions, and long-term overall survival may be achieved in between 50-60% of patients." (PMID 38817862, 2024). "The TNFAIP2 (TNF alpha-induced protein 2, Uniprot: Q03169) was identified in our study as a predictor of better therapy response and was also upregulated in melanoma patients in correlation with long survival both in proteomic and in PD1 and CTLA4 immunotherapy transcriptomic cohorts." (PMID 39015503, 2024). "Finally, we used melanoma as a model tumor type to confirm the capacity to predict the response to CPI and, particularly, anti-CTLA4 antibodies." (PMID 38612803, 2024). "Moderate colitis which does not require the use of intravenous steroids is consistent with an improved overall survival of patients with stage IV melanoma when treated with a single anti-CTLA-4 drug, but not with combination drugs." (PMID 38410760, 2024). "The biopsy analysis of 93 melanoma patients proved that the higher the frequency and maturity of TA-HEC, the better the survival rate of patients receiving the combination of anti-PD-1 antibody and anti-CTLA-4 antibody." (PMID 38835341, 2024). "In melanoma researches, TIDE was identified to be more accurate than other markers, including mutant load and PD‐L1 expression, in the prognosis of first‐line anti‐CTLA4 and/or anti‐PD1 antibody treatment." (PMID 37434432, 2023). "To date, two CTLA-4 inhibitors, ipilimumab and tremelimumab, have been approved for clinical use in the European Union and the Food and Drug Administration (FDA) has approved them in the U.S., mainly for the treatment of melanoma." (PMID 37240574, 2023). "Interestingly, in a mouse melanoma model, the combination of antibodies against TNFSF11 and CTLA4 inhibits tumor growth and metastasis, accompanied by increased T-cell effector function due to significantly higher T-cell infiltration into the tumor." (PMID 37828948, 2023). "Similarly, in the B16 melanoma mouse model, the inclusion of anti-CD93 improved the antitumor effect mediated by PD-1 and CTLA4 mAbs, as revealed by tumor growth and mouse survival curves." (PMID 36761750, 2023). "Although Ipilimumab (anti-CTLA-4) is FDA-approved for stage III/IV melanoma adjuvant treatment, it is not used clinically in first-line therapy, given the superior relapse-free survival (RFS)/toxicity benefits of anti-PD-1 therapy." (PMID 36980641, 2023). "Beyond melanoma, FDA approval of anti-PD-1 and anti-CTLA-4 dual therapy has expanded to hepatocellular carcinoma (HCC), unresectable pleural mesothelioma, RCC, metastatic non-small cell lung cancer (NSCLC), and advanced or metastatic esophageal squamous cell carcinoma." (PMID 37928556, 2023). "Nowadays, the main ICI options for melanoma patients are anti-programmed death 1 (anti-PD1), like nivolumab and pembrolizumab, and anti-CTLA4 in monotherapy (ipilimumab) or, only in a metastatic setting, in combination with nivolumab (anti-PD1 plus anti-CTLA4)." (PMID 36986683, 2023).
melanoma (continued). "Ipilimumab, a monoclonal antibody directed against CTLA-4, a negative regulator of early phases of T lymphocyte activation in lymph nodes, was approved by the FDA in 2011 for the treatment of patients with advanced melanoma." (PMID 36768978, 2023). "Another study of 16 melanoma patients observed that those who were non-responders to CTLA-4 inhibition harbor a much higher rate of genomic changes in the IFN-γ pathway genes compared to those who responded." (PMID 38263984, 2023). "In most HNSCCs, CTLA-4 showed a cytoplasmic rather than membrane-bound expression, which is in line with our previous findings from melanoma." (PMID 37415208, 2023). "Although CTLA-4 ICB-mediated depletion of tumour-infiltrating regulatory T cells has not been observed in human cancers such as melanoma, prostate and bladder cancers, an increase in tumour-infiltrating CD4+ and CD8+ cells has been reported." (PMID 35708739, 2023). "As recently described, immune checkpoint inhibitors (ICIs), including CTLA4 inhibitors and PD1 and PD-L1 inhibitors, have been approved for treating many cancers, such as kidney cancer, melanoma, urothelial cancer and lung cancer, and have achieved good outcomes." (PMID 37862114, 2023). "We used the syngeneic B16F10 murine melanoma model to study the effects of immune checkpoint blocking antibodies against CTLA-4 and PD-1 in combination, with and without the addition of Guadecitabine." (PMID 36934257, 2023). "Immunotherapies using anti-CTLA4 and anti-PD1 monoclonal antibodies offer durable long-term survival benefits that were not previously achieved with traditional cytokine immunotherapy and chemotherapy in melanoma and other malignancies." (PMID 37175874, 2023). "Moreover, we have shown that DNA methylation of CTLA4 predicts response to anti-CTLA-4 and anti-PD-1 antibody therapy in melanoma and to anti-PD-1 ICB in renal cell carcinoma." (PMID 37415208, 2023). "Thus far, one CTLA-4 inhibitor and several PD-1/PD-L1 inhibitors have been approved by the FDA for the clinical treatment of melanoma, lung cancer, HNSCC, and other solid tumors." (PMID 36604694, 2023). "Indeed, ipilimumab, which blocks CTLA-4, was the first immune checkpoint antibody approved by the FDA for treatment of melanoma, and ICIs have become the standard of care in multiple different cancer types, including renal cell carcinoma." (PMID 37345660, 2023). "Moreover, in the GSE91061 melanoma cohort treated with PD1 and CTLA4 inhibitors, CEP55 expression decreased considerably after ICI treatment in the CR/PR group." (PMID 37484531, 2023). "The trial design was informed by results from our preclinical melanoma tumor model that showed enhanced tumor growth control, prolonged survival of mice and an increased IFN-γ response upon the combination of anti-PD-1 + anti-CTLA-4 with domatinostat." (PMID 36920329, 2023). "Similarly, the PS T cell DEGs set showed a predictive value for patient response in three melanoma cohorts treated with anti-PD1 therapy (Liu2019_PD1_Melanoma) and anti-CTLA4 therapy (VanAllen2015_CTLA4_Melanoma and Nathanson2017_CTLA4_Melanoma_Post)." (PMID 37700026, 2023). "A combination of the anti-PD-1 antibody nivolumab and the anti-CTLA-4 antibody ipilimumab has been approved for treating melanoma, RCC, CRC with high microsatellite instability, and non-small cell lung cancer." (PMID 37781078, 2023). "Taken together, these results are consistent with LAG-3 playing a key role in PD-1 and/or CTLA-4 blockade resistance, and provides additional rationale for targeting LAG-3 (in combination with PD-1) as a strategy to overcome ICI resistance in melanoma and possibly other solid tumor types." (PMID 37795090, 2023). "Alternatively, combination therapy with both CTLA4 and PD1 blockade, similar to the strategy used in melanoma, may be effective." (PMID 37949673, 2023).
melanoma (continued). "Increased PD-1, PD-L1, PD-L2 and CTLA-4 expression was also found in melanomas with robust EMT induced by a lack of epithelial splicing regulatory protein 1 (ESRP1) expression." (PMID 36823234, 2023). "In addition to PD1/PD-L1, CTLA-4, LAG-3, TIM-3, and TIGIT are potential melanoma checkpoints in the future." (PMID 37388230, 2023). "To further investigate the role of c-Met+ CTLs in a three-dimensional (3D) setting, we studied their function within B16 melanoma spheroids and examined the impact of cell–cell contact on the modulation of inhibitory checkpoint molecules’ expression, such as KLRG1, PD-1, and CTLA-4." (PMID 38137344, 2023). "Moreover, to identify TME features correlating with ICI response, they also profiled pretreatment melanoma samples from 30 patients with advanced disease who subsequently received ICI therapy (anti-PD1, anti-CTLA4 or the combination)." (PMID 36598558, 2023). "Consistent with this, our study confirmed that miR-155 downregulates CTLA4 at the mRNA level without interfering with FOXP3 expression in circulating Treg cells from melanoma patients." (PMID 37197667, 2023). "A total of 16 patients with advanced melanoma with no response to anti-PD-1 therapy alone or in combination with anti-CTLA-4 therapy after a minimum of two cycles were enrolled." (PMID 36831449, 2023). "We retrospectively collected data of Asian patients with advanced BRAF V600‐mutant melanoma treated with first‐line BRAF/MEK inhibitors (BRAF/MEKi), anti‐PD‐1 monotherapy (Anti‐PD‐1), and nivolumab plus ipilimumab (PD‐1/CTLA‐4) between 2016 and 2021 from 28 institutions in Japan." (PMID 37584204, 2023). "In melanoma patients, the anti-CTLA-4 inhibitor ipilimumab is the standard of care regardless of PD-L1 status, and the combination with an anti-PD1 ICI improves its efficacy." (PMID 38067301, 2023). "In locally advanced (stage III) or resectable metastatic (stage IV) melanomas, medical adjuvant treatment is proposed and recent advances had shown the benefit of anti-PD1/PDL1 and anti-CTLA4 immunotherapy as well as anti-BRAF and anti-MEK targeted therapy in BRAF V600 mutated tumors." (PMID 37328818, 2023). "Considering that CYTL1 may be a potential oncogene in melanoma, it was assessed how CYTL1 interacted with PDCD1, CD274, HAVCR2, TIGIT, SIGLEC15, CTLA4, LAG3, and PDCD1LG2." (PMID 37745303, 2023). "Preclinical data have demonstrated that TNF-α blockade promotes the infiltration of activated T cells induced by ICI treatment and that combination therapy with anti–CTLA-4 and anti–PD-1 with TNF-α blockade improves tumor responses and decreases irAEs in mouse models of melanoma and colon cancer." (PMID 37958355, 2023). "Furthermore, in patients with advanced melanoma, even though there is a subset of patients who are free of progression at 5 years (36%) when treated with the combination PD1+CTLA4, 64% of patients still progress with this therapy." (PMID 37894379, 2023). "In a murine model of BRAF V600E/PTEN null melanoma transgenic mice, an oral TGF-β inhibitor combined with intraperitoneal anti-CTLA-4 antibody led to an increased CD8+ effector T cell: Treg cell ratio and suppression of primary and metastatic melanoma tumor growth." (PMID 38275827, 2023). "Recent studies showed that VISTA might play a significant role in immunotherapy tolerance as its expression increased after CTLA4 blockade in prostate cancer and after PD1 blockade in melanoma." (PMID 36952478, 2023). "Clinical trials in patients with NSCLC and melanoma have reported a dose correlation between the second-time irAEs with CTLA4 inhibitor, but not PD-1/PD-L1 inhibitor." (PMID 37055838, 2023). "For example, in an autochthonous BRAFV600EPTEN-/- melanoma model, a TβRI kinase inhibitor augmented the effects of anti-CTLA-4 treatment but failed to augment the effects of anti-PD-1/PD-L1 blockade." (PMID 36823234, 2023).